IGF2BP1 (insulin like growth factor 2 mRNA binding protein 1)
Diseases named in the same sentence as IGF2BP1 in open-access papers (continued):
Sharing a sentence is not in itself a finding about the gene and the disease.
cancer (continued). "IGF2BP1 has been implicated in the progression and immune escape of other cancers as well." (PMID 39606242, 2024). "This suggests that IGF2BP1 may play a more prominent role in post-transcriptional regulation, particularly in cancer pathways where m6A dysregulation is implicated." (PMID 39456902, 2024). "However, the modulatory mechanisms underlying the abnormally elevated protein levels of IGF2BP1 in cancers are poorly understood." (PMID 36632454, 2023). "We demonstrated a physiological significance of SCFβ-TrCP1 E3 ubiquitin ligase’s protein substrates, β-catenin and the inhibitor of NF-kB (IKKb), for colon and melanoma cancer progression as high levels of human IGF2BP1 in these cancers were associated with NF-kB-activated antiapoptotic programs." (PMID 37503349, 2023). "Additionally, the knockdown of stromal IGF2BP1 facilitates a carcinogenic microenvironment and increases the histologic grade of colitis-associated cancer." (PMID 37554271, 2023). "Over-expression of IGF2BP1 is associated with poor prognosis in a variety of cancers." (PMID 36293188, 2022). "Aberrant IGF2BP1 expression has been associated with tumorigenesis in different cancers." (PMID 36434608, 2022). "In addition, Igf2bp1 has also been associated with enhancing cancer cell resistance to chemotherapy." (PMID 34895045, 2022). "Notably, recent findings indicate that m6A-dependent RNA-association of IGF2BP1 is further enhanced in cancer cells by an oncopeptide derived from LINC00266-1." (PMID 33829040, 2021). "IGF2BP1 expression has been linked to therapeutic resistance in several cancers." (PMID 34203267, 2021). "This specific expression pattern together with its de–regulation and functional role in a set of human cancers puts MSI1 in row with other bona fide oncofetal RBPs such as IGF2BP1 and 3, LIN28B or MEX proteins, representing diagnostic markers with therapeutic potential for cancer treatment." (PMID 34062997, 2021). "Our results show that broadly, the majority of transcripts that were adversely affected by IGF2BP1 depletion were associated with cancer, organismal injury and abnormalities, several disease areas including gastrointestinal, endocrine system, dermatology, reproductive systems, and cellular movement." (PMID 33796454, 2021). "In pan-cancer, IGF2BP1 was a risk gene, while METTL3 was a protective gene." (PMID 34957092, 2021). "The further evaluation of IGF2BP1’s role in modulating the expression of such effectors like AURKA will unravel novel avenues to pursue the inhibition of IGF2BP1-mRNA association in combinatorial treatment strategies to improve cancer patient outcome." (PMID 33829040, 2021). "In addition, IGF2BP1 was reported to associate with some long non-coding RNAs (lncRNAs) in cancer cells." (PMID 33829040, 2021). "Finally, we found that genes significantly correlated with IGF2BP1/2/3 were significantly enriched in cancer hallmark-related pathways." (PMID 33575259, 2020). "Moreover, E2F_TARGET genes showed a strong correlation of downregulation upon IGF2BP1 depletion in cancer cell lines and IGF2BP1-associated expression in the corresponding primary cancers." (PMID 32761127, 2020). "Thus, our studies provide pre-clinical evidence that combined treatment with BTYNB, impairing IGF2BP1-RNA association, is beneficial for cell cycle inhibition, e.g. by Palbociclib, in cancer treatment." (PMID 32761127, 2020). "Moreover, gene set enrichment analysis revealed that IGF2BP1–3 target genes upregulated in the basal subtype are associated with several cancer-relevant biological processes, including focal adhesion, cell–substrate junction organization, cytoskeleton regulation, and mitotic nuclear division." (PMID 40918643, 2025). "Furthermore, our proteomic interactome suggests BAG5 may regulate translation through interaction with RNA-binding proteins such as IGF2BP1–3 and factors associated with EIF2α phosphorylation, which have been implicated in cancer cell metabolic control." (PMID 40787462, 2025).
cancer (continued). "Moreover, as the m6A consensus sequence, to which IGF2BP1 binds, is a rather frequent motif also in lncRNAs, further cancer-associated lncRNAs that interact with IGF2BP1 might be identified in the future." (PMID 32340118, 2020). "IGF2BP1 knockdown induces cancer cell apoptosis; this effect highlights its role in programmed death." (PMID 39802639, 2025). "After the resection of primary tumors, the cancer cells which expressed the IGF2 binding protein 1 (IGF2BP1) were observed metastasize." (PMID 39674501, 2025). "As an m6A reader, IGF2BP1 acts as an oncogenic factor in various cancer cells by stabilizing the expression of methylated mRNAs associated with oncogenic genes." (PMID 40356725, 2025). "Which further confirms its potential as an effective therapeutic agent against cancers with elevated IGF2BP1 expression." (PMID 40823087, 2025). "IGF2BP1 knockdown suppresses the stemness maintenance, self-renewal capacity, xenograft tumorigenesis, and immune evasion of cancer stem cells." (PMID 40986143, 2025). "The data from the GDSC database aligned with the CTRP data, displaying the sensitivity of IGF2BP1/2/3 to trametinib, which is commonly used for treating specific cancer types like LUSC and SKCM." (PMID 40088376, 2025). "Cucurbitacin B (CuB), a chemogenetic small molecule, promotes apoptosis by blocking IGF2BP1's recognition of m6A‐modified mRNA, which affirms m6A's critical role in cancer cell survival and death regulation." (PMID 39802639, 2025). "IGF2BP1 usually functions as an oncogene in human cancers and relates to different aspects of cancer hallmarks." (PMID 40584294, 2025). "Together, these findings identify IGF2BP1 as both an amplifier and a reprogrammer of transcriptomes in Wnt-driven normal and cancer cells." (PMID 41516083, 2025). "This work seeks to clarify IGF2BP1's potential role as a prognostic biomarker and therapeutic target in EC within the context of personalized cancer care." (PMID 41210679, 2025). "The levels of IGF2BP1 expression in cancer cells were also significantly higher than those in HBE4‐E6/E7 cells." (PMID 41394407, 2025). "In many cancers, IGF2BP1 amplifies Wnt/β-catenin pathway output through feed-forward regulatory mechanisms that influence downstream effectors such as c-MYC." (PMID 41516083, 2025). "m6A regulators include writers (METTL3, METTL14, KIAA1429, and ZC3H13), erasers (ALKBH5 and FTO) and readers (YTHDF1/2/3, IGF2BP1/2/3), which are thought to play important roles in regulating cancer progression." (PMID 40774945, 2025). "For this reason, we evaluated another cancer-testis antigen; insulin-like growth factor 2 mRNA binding protein (IGF2BP1) which was expressed in 10% of patients in this cohort." (PMID 38604503, 2024). "The expression of IGF2BP1, an oncogene and potential therapeutic target for cancers, differed among the four subtypes." (PMID 38777866, 2024). "We found that IGF2BP1 expression was positively correlated with scores in common cancer-related pathways, including the Hippo signaling pathway and the Wnt signaling pathway." (PMID 39512352, 2024). "A large body of evidence has demonstrated that IGF2BP1 is involved in cancer metastasis and proliferation, making it a potential therapeutic target." (PMID 39342091, 2024). "Recently, several noncoding RNAs have been reported to mediate cancer progression by binding to the 3’UTR or KH domains of IGF2BP1." (PMID 39342091, 2024). "BTYNB, as a novel inhibitor of IGF2BP1, inhibits cell cycle and cancer progression by impairing IGF2BP1-dependent mRNA coding factor stability." (PMID 39473440, 2024). "IGF2BP1 is an RNA binding protein with expression in a wide range of fetal tissues and several cancers but the expression in adult tissues is limited to the testis, ovary, prostate, and kidney." (PMID 38604503, 2024).
cancer (continued). "Inhibition of IGF2BP1 was shown to sensitize a variety of cancer cells to therapeutics, and it was demonstrated to be especially effective in reducing the resistance of chemotherapy-resistant CRC cells with activated Wnt/β-catenin signaling." (PMID 39456596, 2024). "The oncogenic role of IGF2BP1 has been reported in several human cancers, however, its functions in HCC immune microenvironment and energy metabolism are still unclear." (PMID 39606242, 2024). "It is well-known that insulin-like growth factor 2 binding protein 1 (IGF2BP1) is an “oncofetal” protein specially expressed in a broad range of fetal tissues and many cancers." (PMID 39342091, 2024). "Patients in the low-IGF2BP1 group exhibited higher immune responses in the HNSC patient cohort at Fujian Cancer Hospital." (PMID 39512352, 2024). "The IGF2BP family consists of three members including IGF2BP1, IGF2BP2, and IGF2BP3, all of which are implicated in the drug resistance of human cancers." (PMID 39731162, 2024). "IGF2BP1’s main function in cancer appears to be the protection of its mainly pro-oncogenic target RNAs from miRNA-mediated degradation via binding to its four hnRNPK homology (KH) domains." (PMID 37515119, 2023). "In this study, we provide new evidence that IGF2BP1 and its paralogs influence innate and adaptive immune responses in normal and cancer cells." (PMID 37503349, 2023). "Abnormal expression of IGF2BP2 and reactivation of IGF2BP1 and 3 are often seen during cancer progression." (PMID 37503349, 2023). "The criteria for selecting genes as target candidates comprised a consistent downregulation upon IGF2BP1 knockdown in several cancer-derived cell lines, a positive expression correlation with IGF2BP1 in tumors as well as reported IGF2BP1 binding sites." (PMID 37515119, 2023). "The here presented mouse models will expedite the evaluation of improved IGF2BP1i and provide valuable resources for identifying additional IGF2BP1-driven oncogenic effectors for combined cancer treatment." (PMID 37246217, 2023). "IGF2BP1 overexpression is often correlated with poor prognosis in a variety of cancer types, including melanoma, breast, ovarian, colon, liver, and lung cancers." (PMID 37644505, 2023). "And mTORC2 kinase inhibitor Torin1 and Src kinase inhibitor AZD0530 have been identified to synergistically inhibit the growth of IGF2BP1-expressing cancer cells in vitro and in vivo by disrupting IGF2BP1 phosphorylation." (PMID 37280679, 2023). "Relying on the representative KH3-4 domain, IGF2BPs can stabilize mRNAs; for example, overexpressed IGF2BP1 is shown to recognize the m6A sites in the 3' UTR of pyruvate kinase M1/2 (PKM2) via the KH3-4 domain to promote cancer progression." (PMID 37554271, 2023). "It has been found that IGF2BP1 knockdown can induce apoptosis of cancer cells, significantly activate immune cell infiltration, and also reduce the expression of PD-L1 in HCC." (PMID 37020540, 2023). "As IGF2BP1 has an oncofetal expression pattern and is overexpressed in several types of cancers, including CRC." (PMID 37829185, 2023). "A novel IMP1 inhibitor, BTYNB, disturbed the interaction between IGF2BP1 and RNAs; indicating a drug strategy for IGF2BP1-driven cancer." (PMID 37537521, 2023). "The main function of IGF2BP1 in cancer is the partially m6A- (N6-methyladenosine), but typically microRNA- (miRNA) and 3’UTR-dependent stabilization of mRNAs." (PMID 37246217, 2023). "In the consistent research, a consensus has been reached that IGF2BP1 has a strong conversed potential in cancer-derived cell lines." (PMID 37426488, 2023). "The ROC curve based on the IGF2BP1 level showed moderate accuracy to discriminate the outcome between normal and cancer (area under the curve = 0.766, confidence interval = 0.730–0.802)." (PMID 36966311, 2023). "Direct targeting of IGF2BP1 blocks the recognition of m6A mRNA target by IGF2BP1 and induces apoptosis of cancer cells." (PMID 37841018, 2023).
cancer (continued). "The IGF2BP1 protein level has been reported to be widely upregulated in several aggressive cancers 27, 60-64." (PMID 36632454, 2023). "IGF2BP1: IGF2BP1 was found to be commonly and significantly up‐regulated in almost all cancer cell lines." (PMID 36260366, 2023). "Compared with IGF2BP3, IGF2BP1 has a more complex role in cancer, possessing both pro- and anti-cancer effects, and therefore, IGF2BP3 correlates better with cancer progression., suggesting the importance of further studies on FOXM1 regulation of IGF2BP3." (PMID 37234166, 2023). "A majority of paired samples also exhibited upregulation, while a minute subset demonstrated downregulation of IGF2BP1 in cancer tissue." (PMID 36092925, 2022). "Igf2bp1 appears to mediate many of its pro-oncogenic effects by binding a wide variety of cancer promoting RNAs, protecting them from degradation, enhancing their translation, and/or regulating their intracellular localization." (PMID 34895045, 2022). "As EZH2 has been described as major epigenetic regulator involved in tumorigenesis of several cancers, we further focused on its regulation by IGF2BP1." (PMID 35565249, 2022). "Among these prognosis related stress granule regulators, EIF4G1, IGF2BP1 had been demonstrated to be key regulators in cancer cells." (PMID 35433677, 2022). "These genes are related to the immune system and tumors: GNG7 is related to PI3K-Akt and Chemokine, FKBP4 is related to Estrogen, and IGF2BP1 is related to miRNA in the cancer pathway, and CD40LG is related to the NF-kappa B and T cell receptors." (PMID 36249053, 2022). "The emerging evidence has proposed the oncofetal IGF2 mRNA binding protein 1 (IGF2BP1) as the cancer turnover regulator for its pivotal role in stabilizing the pro-oncogenic mRNA expression." (PMID 36536402, 2022). "Most importantly, we mainly review the up-to-date knowledges of IGF2BPs (IGF2BP1/2/3) as m6A readers in an m6A-modified manner in cancer progression." (PMID 35541906, 2022). "IGF2BP1 has been shown to have an important role in tumorigenesis in many different cancers and correlated with a poor prognosis." (PMID 36307883, 2022). "We further considered the effect of m6A regulators on the m6A RNA modification of transcripts, and we found that IGF2BP1/2/3, as m6A readers, had significant differential expression in seven cancer types." (PMID 35654793, 2022). "Recently, IGF2BP1 is reported to promote E2F1-3-driven G1/S transition in an m6A-dependent manner in cancer cells." (PMID 35541906, 2022). "IGF2BP1 is highly expressed in a variety of malignant tumors, and it is inclined to be considered as an oncogene." (PMID 35935853, 2022). "IGF2BP proteins are generally thought to support pro-oncogenic, pro-proliferative cancer phenotypes with IGF2BP1 being the most conserved posttranscriptional regulator within the family." (PMID 35565249, 2022). "IGF2BP1 overexpression can promote cell proliferation and regulate the tumor cell cycle and cancer progression, both in vivo and in vitro." (PMID 35813486, 2022). "As IGF2BP1 has been shown to promote G1/S cell cycle transition in other cancer types we performed cell cycle analysis upon IGF2BP1 knockdown." (PMID 35565249, 2022). "The full name of IGF2BP1 is insulin-like growth factor-2 mRNA-binding protein 1, which expresses in more than 16 cancers and most fetal tissues but only in a limited number of normal adult tissues." (PMID 34141492, 2021). "Our in silico studies confirmed recently reported and revealed a variety of novel candidate target mRNAs of IGF2BP1 in cancer cells." (PMID 33829040, 2021). "Although IGF2BP1-3 were expressed in a lower level than other m6A RNA methylation regulators, they had a higher level in more malignant cancer." (PMID 34141492, 2021). "The opposite is observed for the comparatively small number of transcripts consistently upregulated upon IGF2BP1 depletion and generally negatively correlated with IGF2BP1 expression (UNPs) in primary cancers." (PMID 33829040, 2021).
cancer (continued). "Insulin-like growth factor 2 mRNA-binding protein 1 (IGF2BP1) is an oncogenic protein expressed in various cancers, including HCC." (PMID 34779401, 2021). "Aiming to identify RNAs with conserved IGF2BP1-dependent regulation in cancer cells, we considered IGF2BP1 knockdown experiments in six distinct cancer cell lines." (PMID 33829040, 2021). "A novel finding of our studies is an apparently conserved role of IGF2BP1 in modulating the unfolded protein response in cancer cells." (PMID 33829040, 2021). "Accordingly, the 117 DPPs associated with significant eCLIP-sites, denoted as DPPCLIP, were considered as prime candidates of conservedly stabilized target mRNAs of IGF2BP1 in cancer cells." (PMID 33829040, 2021). "This approach settles on the evaluation of altered gene expression upon IGF2BP1 depletion in six cancer cell lines derived from distinct cancer entities." (PMID 33829040, 2021). "In NSCLC cells, IGF2BP1 silencing potently suppressed cancer cell proliferation, migration and invasion, as well as induced cell cycle arrest and apoptosis." (PMID 34868966, 2021). "In conclusion, our studies provide a comprehensive view on conserved roles of IGF2BP1-dependent mRNA stabilization in cancer." (PMID 33829040, 2021). "Our gain- and loss-of-function studies indicated that IGF2BP1 facilitated the proliferation, migration and invasion of cancer cells, suggesting the oncogenic roles of IGF2BP1 in BC." (PMID 33853613, 2021). "IGF2BP1 has been traditionally regarded as an oncogene and potential therapeutic target for cancers as well." (PMID 33796449, 2021). "Knockdown of IGF2BP1 inhibited cancer cell proliferation, migration, and invasion, and also induced cell cycle arrest and apoptosis." (PMID 34993132, 2021). "The lncRNA THOR was the first cancer/testicular lncRNA to be discovered and was further shown to conservatively interact with IGF2BP1 and to contribute to its mRNA stabilization activity." (PMID 34440063, 2021). "RNA-association CLIP (crosslinking and immunoprecipitation) studies of IGF2BP1 in HEK293, embryonic stem cells and cancer cells suggested a variety of candidate target mRNAs of IGF2BP1, preferred 3’UTR binding and proposed short binding motifs of the protein." (PMID 33829040, 2021). "Here, we established ectopically IGF2BP1-expressing HCT-116 and DLD-1 CRC cells for examining the impact of IGF2BP1 directly on cancer cells." (PMID 34203267, 2021). "In particular, HMGA2, LIN28B, and IGF2BP1 have been referred to as an “oncogenic triangle” that is critical for cancer initiation and that was also co-ordinately overrepresented in our data." (PMID 34706236, 2021). "The specific function of the insulin-like growth factor 2 mRNA-binding protein 1 (IGF2BP1; an m6A “reader”) in governing the stability of m6A-modified lncRNAs in carcinomas has already been reported." (PMID 34858996, 2021). "As oncogenes of AML, METTL3, METTL14, WTAP, FTO, YTHDF2, and IGF2BP1 participate in tumor processes through a variety of pathways, including the promotion of the growth of cancer cells and inhibition of apoptosis." (PMID 33519919, 2020). "Our analysis reveals higher expression of IGF2BP1/2/3 across cancer types; however, we still lack knowledge about their regulatory mechanisms in cancer." (PMID 33575259, 2020). "In agreement with reduced IGF2BP1-association of the four mRNAs, steady state levels of all four transcripts were markedly reduced upon BTYNB exposure of A549 as well as all other cancer cell lines investigated." (PMID 32761127, 2020). "This significant enrichment was also observed in each of the five investigated cancers suggesting E2F-driven gene expression as a conserved effector pathway of IGF2BP1 in cancer." (PMID 32761127, 2020). "IGF2BP1 and 3 have been considered as oncogenes due to their targeting of some cancer-related mRNAs." (PMID 32967226, 2020). "This is concise with IGF2BP1’s broad expression in cancer cell lines and substantial upregulation in progressed cancers." (PMID 32761127, 2020).